CASC2 (cancer susceptibility 2)
Diseases named in the same sentence as CASC2 in open-access papers (continued):
Sharing a sentence is not in itself a finding about the gene and the disease.
glioblastoma (6 papers, 2020 to 2022). The most malignant astrocytic tumor (WHO grade IV). "CASC2 overexpression inhibits glioblastoma cell proliferation, migration and invasion via miR-21, and miR-21 overexpression abrogated CASC2-induced inhibitory effects." (PMID 34316694, 2021). "In summary, lncRNA CASC2 was found as a tumor suppressor and downregulated in low-grade astrocytomas and highly malignant glioblastomas as compared to healthy brain tissue." (PMID 33120918, 2020). "Overexpression of CASC2 inhibited malignancy of glioblastoma cells via miR-21, and overexpression of miR-21 abrogated the CASC2-induced inhibitory effects in the same cells." (PMID 32283739, 2020). "Similarly, CASC2 overexpression suppresses the Wnt/β-catenin signaling pathway in glioblastoma cells." (PMID 34316694, 2021). "In the presence of TMZ, the CASC2/miR-193a-5p/mTOR axis could be a promising therapeutic approach for glioblastoma treatment." (PMID 32283739, 2020). "In glioma tissues and glioblastoma cell lines, the CASC2 lncRNA is downregulated." (PMID 32283739, 2020). "CASC2 expression was significantly downregulated in glioblastomas (p = 0.0003)." (PMID 33120918, 2020). "A recent study confirmed that EIF4A3 played a role in the EIF4A3/CASC2/RORA loop and ultimately facilitated the aggressive phenotype of glioblastoma." (PMID 35936722, 2022). "The following lncRNAs engaged in glioblastoma therapy resistance were selected: MALAT1, CASC2, H19, TUSC7, XIST, RP11-838N2.4, DLX6-AS1, GLIDR, MIR210HG, SOX2-OT." (PMID 33245508, 2022).
osteoarthritis (6 papers, 2019 to 2024). A noninflammatory degenerative joint disease occurring chiefly in older persons, characterized by degeneration of the articular cartilage, hypertrophy of bone at the margins and changes in the synovial membrane. "Huang and colleagues found that CASC2 (Cancer Susceptibility 2) was overexpressed in osteoarthritis patients and it could regulate IL17 expression and contribute to chondrocyte proliferation and apoptosis." (PMID 32549759, 2020). "For example, increased levels of lncRNA CASC2 have been observed in osteoarthritis patients, suggesting that CASC2 is a key regulator of Interleukin-17 (IL-17) expression and chondrocyte proliferation and apoptosis." (PMID 39690146, 2024). "LncRNA CASC2 level upregulates in plasma of osteoarthritis patients and CASC2 overexpression promotes IL-17 expression and inhibits the proliferation in human chondrocyte cell line (CHON-001)." (PMID 35501316, 2022). "This study aimed to investigate the interaction between miR-93-5p and lncRNA CASC2 in chondrocyte apoptosis, which plays critical roles in osteoarthritis (OA)." (PMID 31931772, 2020). "Recently, CASC2 is reported to be upregulated in osteoarthritis patients and its overexpression is positively correlated with IL17 level." (PMID 32549759, 2020). "In the present study we found that lncRNA CASC2 was up-regulated in osteoarthritis and participated in the regulation of IL-17 expression and chondrocyte proliferation and apoptosis." (PMID 31015370, 2019). "In the present study we first reported that lncRNA CASC2 was up-regulated in osteoarthritis patients than in healthy controls." (PMID 31015370, 2019). "Our new findings showed that both lncRNA CASC2 and IL-17 were up-regulated in plasma of osteoarthritis patients." (PMID 31015370, 2019). "Comparing to control group, lncRNA CASC2 and IL-17 were both up-regulated in plasma of osteoarthritis patients (P<0.05)." (PMID 31015370, 2019). "The present study first reported the involvement of lncRNA CASC2 in osteoarthritis and further confirmed that the actions of lncRNA CASC2 in this disease are likely achieved by interacting with IL-17." (PMID 31015370, 2019). "Plasma levels of lncRNA CASC2 and IL-17 in osteoarthritis patients (n = 71) and healthy controls (n = 55) were measured." (PMID 31015370, 2019). "Results showed that plasma levels of lncRNA CASC2 and IL-17 were significantly and positive correlated in osteoarthritis patients." (PMID 31015370, 2019). "Plasma levels of lncRNA CASC2 and IL-17 were significantly and positive correlated only in osteoarthritis patients." (PMID 31015370, 2019). "LncRNA CASC2 can be regulated by miR-93–5p and affect chondrocyte apoptosis in osteoarthritis." (PMID 37779916, 2023). "Similarly, lncRNA CASC2 regulated the expression of IL-17 and modulated apoptosis and proliferation of chondrocytes in osteoarthritis." (PMID 37779916, 2023). "LncRNA CASC2 is a well-characterized tumor suppression lncRNA in human cancers, while its involvement in osteoarthritis is unknown." (PMID 31015370, 2019). "Besides that, lncRNA CASC2 and IL-17 in synovial fluid of 21 osteoarthritis patients and 15 healthy controls were also detected." (PMID 31015370, 2019). "Similarly, lncRNA CASC2 and IL-17 were both up-regulated in synovial fluid of osteoarthritis patients comparing to healthy controls (P<0.05)." (PMID 31015370, 2019). "Therefore, lncRNA CASC2 is up-regulated in osteoarthritis and participates in the regulation of IL-17 expression and chondrocyte proliferation and apoptosis." (PMID 31015370, 2019). "LncRNA CASC2 may also participate in osteoarthritis by inducing cell apoptosis and up-regulating pro-inflammatory factor IL-17." (PMID 31015370, 2019). "In conclusion, lncRNA CASC2 and IL-17 are up-regulated in osteoarthritis." (PMID 31015370, 2019). "Therefore, overexpression of lncRNA CASC2 may also participate in osteoarthritis by up-regulating pro-inflammatory factor IL-17." (PMID 31015370, 2019).
osteoarthritis (continued). "Therefore, the overexpression of lncRNA CASC2 may promote the development of osteoarthritis by promoting the apoptosis of chondrocytes." (PMID 31015370, 2019).
Sepsis (6 papers, 2022 to 2024). Sepsis is defined as life-threatening organ dysfunction caused by a dysregulated host response to infection. "Susceptibility cancer candidate 2 (CASC2) expression was significantly reduced in sepsis patient serum and LPS-treated HK2 and HEK293 cells, with levels inversely correlating with the severity of AKI and pro-inflammatory miR-155." (PMID 36299256, 2022). "CASC2 overexpression ameliorates sepsis-associated AKI by regulating the miR-545-3p/PPARA axis." (PMID 36299256, 2022). "Another study has shown that the expression of lncRNA cancer susceptibility candidate 2 (CASC2) was significantly decreased in sepsis patients compared with healthy subjects, and the level of the CASC2 was negatively correlated with the severity of kidney damage." (PMID 35464083, 2022). "More validation studies and clinical trials are needed to confirm the reliability and reproducibility of using lncRNA CASC2 as a biomarker for sepsis." (PMID 39201697, 2024). "Studies have shown that the expression of the lncRNA CASC2 is reduced in sepsis patients and inversely correlated with APACHE II and SOFA scores, as well as TNF-α, IL-1β, and IL-17A levels." (PMID 39201697, 2024). "Previous research has shown that lncRNA CASC2 prevents inflammation and sepsis-induced multi-organ damage through a variety of signaling pathways." (PMID 38342902, 2024). "Downregulation of CASC2 is detected in both sepsis patients and LPS‐treated HPAEpiC, contributing to the cell inflammatory and oxidative damages." (PMID 35665444, 2022). "As a previous study reported, CASC2 downregulation contributes the lung cell inflammatory and oxidative damages and further aggravates sepsis‐induced lung injury." (PMID 35665444, 2022). "As the field of RNA biomarkers continues to evolve, future guidelines and recommendations for sepsis management may consider incorporating lncRNA CASC2 alongside traditional biomarkers." (PMID 39201697, 2024). "CASC2 may serve as a potential target for the treatment of sepsis-induced AKI by inhibiting miR-155-and NF-κB pathway–mediated inflammation." (PMID 36299256, 2022). "The lncRNA CASC2 levels are lower in sepsis non-survivors and can predict 28-day mortality riskLower levels of lncRNA CASC2 are associated with higher APACHE II and SOFA scores." (PMID 39201697, 2024). "Furthermore, lncRNA CASC2 levels are lower in sepsis non-survivors compared to survivors, suggesting its potential in predicting the 28-day mortality among sepsis patients." (PMID 39201697, 2024).
thyroid cancer (6 papers, 2018 to 2023). "However, studies on the association between CASC2 and thyroid cancer are rare." (PMID 32596158, 2020). "Their findings showed that the expression of CASC2 can be an independent prognostic factor in thyroid cancer patients." (PMID 32760219, 2020). "CASC2 downregulation indicates poor prognosis in thyroid cancer." (PMID 32596158, 2020). "Knockdown of CASC2 inhibited 131I sensitivity in thyroid cancer cells." (PMID 33134385, 2020). "In addition, this study demonstrated that CASC2 affects thyroid cancer cell invasion and metastasis by regulating the EMT pathway, and may be a predictor of LNM in patients with thyroid cancer." (PMID 32596158, 2020). "As a conclusion, CASC2 increases 131I sensitivity in PTC by sponging miR-155, providing a novel target for the treatment of thyroid cancer patients with 131I resistance." (PMID 33134385, 2020). "Overexpression of CASC2 leads to inactivation of AKT and ERK1/2, which can significantly inhibit the proliferation of thyroid cancer cells." (PMID 32596158, 2020).
bladder cancer (5 papers, 2014 to 2020). "In summary, our findings indicated that CASC2 was strikingly downregulated in bladder cancer tissues." (PMID 28199978, 2017). "The result of qRT-PCR exhibited that the bladder cancer cells showed low expression of CASC2 compared with the normal urothelial cells (P<0.01)." (PMID 28199978, 2017). "In the present study, we manifested that lncRNA CASC2 expression was reduced in both bladder cancer tissues and cell lines and and negatively correlated with advanced TNM stage." (PMID 28199978, 2017). "MTS assay and colony formation assay showed that overexpression of CASC2 inhibited bladder cancer cell proliferation in vitro." (PMID 28199978, 2017). "Next, transwell invasion assay was carried out to document the effect of CASC2 on the invasiveness of bladder cancer cells." (PMID 28199978, 2017). "In this study, we found that lncRNA CASC2 was significantly down-regulated in bladder cancer tissues and cell lines by quantitative real time-PCR and associated with advanced TNM stage (III/IV)." (PMID 28199978, 2017). "Our results showed that lncRNA CASC2 expression levels were lower in tumor tissues than those in adjacent normal tissues and down-expressed in the bladder cancer cell lines." (PMID 28199978, 2017). "Then, we examined the expression of CASC2 in a panel of bladder cancer cells (T24, 5637, SW780, J82 and UMUC3) and normal urothelial cells (SV-HUC-1) by qRT-PCR." (PMID 28199978, 2017). "To further probe the influence of CASC2 on bladder cancer cell migration and invasion, we conducted transwell assays in T24 and 5637 cells." (PMID 28199978, 2017). "Moreover, overexpression of lncRNA CASC2 remarkably reduced the cell growth, migration and invasion, as well as promoted early apoptosis of bladder cancer cell in vitro." (PMID 28199978, 2017). "Besides, we investigated the function of CASC2 in bladder cancer cells by applying gain-of-function approaches." (PMID 28199978, 2017). "Therefore, using Western blot assay and qRT-PCR, we detected the effect of CASC2 on β-catenin expression and a few of the downstream genes of the Wnt/β-catenin signaling pathway, such as, cyclin D1, c-myc and E-cadherin in bladder cancer cells." (PMID 28199978, 2017). "Additionally, transwell assay showed that overexpression of CASC2 suppressed bladder cancer migration and invasion." (PMID 28199978, 2017). "Next, we examined caspase-3 activity in bladder cancer cells in response to CASC2 overexpression." (PMID 28199978, 2017). "Altogether, these results clarified that CASC2 may function as a suppressor gene promoting bladder cancer cell proliferation." (PMID 28199978, 2017). "And overexpression of lncRNA CASC2 remarkably inhibited the growth, arrested migration and invasion, as well as induced early apoptosis and attenuated the activation of Wnt/β-catenin signal pathway in T24 and 5637 bladder cancer cells." (PMID 28199978, 2017). "Taken together, lncRNA CASC2 plays an pivotal role in bladder tumorigenesis and progression and may act as a potential biomarker for the treatment of bladder cancer." (PMID 28199978, 2017). "However, the role of lncRNA CASC2 in the progression of bladder cancer is unknown and needed to be further explored." (PMID 28199978, 2017). "However, the role of CASC2 in bladder cancer is still unclear." (PMID 28199978, 2017). "However, the biological function of lncRNA CASC2 in bladder cancer are still unclear." (PMID 28199978, 2017). "We firstly explored the relative expression level of CASC2 in bladder cancer tissues (n=72) compared with corresponding non-tumor tissues (n=72) by qRT-PCR, and normalized to GAPDH." (PMID 28199978, 2017). "The CASC2 level was significantly decreased in bladder cancer tissues compared with corresponding adjacent non-tumorous tissues (P<0.001)." (PMID 28199978, 2017).
colon cancer (5 papers, 2022 to 2024). "CASC2 also causes apoptosis and autophagy in colon cancer by regulating the levels of TRIM16 via miR-214." (PMID 37588204, 2024). "Upregulation of lncRNA CASC2 attenuated cell viability, induced apoptosis and affected autophagy via regulation of miR-19a and NF-kappa B signaling pathway in colon cancer." (PMID 35928868, 2022). "For instance, in a study, it was observed that lncRNA CASC2 was downregulated in colon cancer cell and tissues, and overexpression of CASC2 resulted in growth inhibition with induction of apoptosis and autophagy by increasing the levels of LC3B II and Beclin-1." (PMID 39716252, 2024). "ARlncRNA CASC2 was detected to be lowly expressed in colon cancer cells and inhibited cell viability by down-regulating miR19a and inhibiting the NF-κB/p65, suggesting that CASC2 may be a prospective factor for the therapeutic therapy of colon cancer." (PMID 37588204, 2024). "Similarly, it has been reported that lncRNA CASC2 is lowly expressed in colon cancer cell lines HT29 and SW480, while its re-expression restrains cancer cell viability but accelerates apoptosis and autophagy." (PMID 38267746, 2024). "The authors deduced that lncRNA CASC2 and miR19a might have a close correlation during the progression of colon cancer cells and that NF-kB was the signaling pathway, which could regulate the correlation between lncRNA CASC2 and miR19a." (PMID 37373349, 2023).
breast carcinoma (4 papers, 2019 to 2024). "CASC2 (Cancer Susceptibility Candidate 2) has been explored in various cancers, including breast cancer, for its potential tumor-suppressing roles." (PMID 39479021, 2024). "Reduced CASC2 expression in breast cancer is linked to poor prognosis, higher tumor grade, and increased metastatic potential." (PMID 39479021, 2024). "For example, detecting the expression of lncRNAs like MEG3, CASC2, and others can help clinicians identify breast cancer at an early stage and improve diagnostic accuracy." (PMID 39479021, 2024). "High CASC2 expression has been previously shown to inhibit pancreatic and ovarian cancer growth and, opposingly, contribute to breast cancer chemoresistance." (PMID 34187466, 2021). "Recent studies have shown that the restoration of CASC2 expression significantly suppresses growth and metastasis in breast cancer cells via regulation of the miR-96-5p/SYVN1 pathway and inactivation of the TGF-β signaling pathway." (PMID 31728180, 2019). "CASC2 overexpression inhibites the viability, migration and invasion, and elevates apoptosis of breast cancer cells through acting as a ceRNA for miR-96 and upregulating synoviolin (SYVN1) expression." (PMID 31728180, 2019). "CASC2 could be a valuable biomarker for breast cancer diagnosis and prognosis." (PMID 39479021, 2024). "Moreover, the expression of CASC2 is significantly decreased in breast cancer tissues." (PMID 31728180, 2019). "Correlation of CASC2, NEAT1, and LINC00299 expression with clinicopathological features of breast cancer." (PMID 37706018, 2023). "In the present study, we aim to investigate the expression levels of NEAT1, LINC00299, and CASC2 genes in breast cancer samples compared to adjacent nonmalignant samples, as well as their relationship with the spliced XBP1 mRNA level." (PMID 37706018, 2023). "Furthermore, based on the ROC curve results, CASC2 and NEAT1 genes may be suitable biomarkers for breast cancer diagnosis." (PMID 37706018, 2023).
malignant melanoma (4 papers, 2014 to 2024). "For instance, in malignant melanoma cells, CASC2 associates with miR-18a and then upregulates RUNX1 expression, subsequently suppressing cell proliferation, migration and invasion." (PMID 31728180, 2019). "Moreover, CASC2 was found downregulated in malignant melanoma, and low CASC2 expression was correlated with tumor size, TNM stage, and poor overall and disease-free survival (DFS) of malignant melanoma patients." (PMID 36816357, 2023). "Additionally, CASC2 may inhibit the development of malignant melanoma by regulating miR-18a-5p/RUNX1 axis." (PMID 38792557, 2024).
oral squamous cell carcinoma (4 papers, 2020 to 2022). "The functions and expression patterns of CASC2 have only been investigated in cancer biology, such as oral squamous cell carcinoma (OSCC)." (PMID 31937279, 2020). "For instance, lncRNA CASC2 acts as a ceRNA of miR-21 to up-regulate the expression of PDCD4 in oral squamous cell carcinoma." (PMID 31737900, 2020). "Oral squamous cell carcinoma (OSCC) owes its resistance to chemotherapy to CASC2." (PMID 36294833, 2022).
chronic renal failure (3 papers, 2019 to 2021). "Recently, it was reported that the low expression of CASC2 has diagnostic values in serum and renal tissues for diabetes complicated with chronic renal failure." (PMID 30891461, 2019). "A follow-up showed that patients with low serum level of CASC2 had significantly higher incidence of chronic renal failure by inhibiting the JNK pathway, which is common in patients with DN." (PMID 30891461, 2019). "Furthermore, the ROC curve analysis showed that the CASC2 level in renal tissues and serum is effective in diagnosing type 2 diabetes complicated with chronic renal failure." (PMID 30891461, 2019). "Thus, CASC2 may serve as a predictive factor and target for the treatment and prevention of DN with chronic renal failure." (PMID 30891461, 2019).
epithelial ovarian cancer (3 papers, 2019 to 2021). "In epithelial ovarian cancer cells, eIF4A3 binds CASC2 and enhances cell viability, apoptosis, migration, and invasion." (PMID 34869305, 2021). "Overexpression of CASC2 inhibited epithelial ovarian cancer development by inhibiting EIF4A3 expression and suppressing the PI3K/AKT/mammalian target of rapamycin (mTOR) pathway." (PMID 31134151, 2019). "Notably, eIF4A3 has been identified as a binding protein of lncRNA CASC2, thereby affecting epithelial ovarian cancer development." (PMID 34869305, 2021).
esophageal squamous cell carcinoma (3 papers, 2019 to 2022). Esophageal squamous cell carcinoma (ESCC) is a type of esophageal carcinoma (EC) that can affect any part of the esophagus, but is usually located in the upper or middle third. "It should be mentioned that the effect of cisplatin on cells with reduced CASC2 expression in esophageal squamous cell carcinoma was analyzed." (PMID 36294833, 2022).
liver cancer (3 papers, 2021 to 2025). An epithelial or non-epithelial malignant neoplasm that arises from the liver. "Cancer Susceptibility 2 (CASC2) is a useful liver cancer cell regulator whose expression can be down-regulated in multiple cancers, including HCC." (PMID 34758879, 2021). "Therefore, CASC2 regulates the expression of FBXW7 by regulating miR-367 in liver cancer cells." (PMID 40534867, 2025).